Y_RNA (Y RNA )
Gene: Miscellaneous RNA gene on chromosome 1 (240,154,651 to 240,154,772, reverse strand). Ensembl gene ENSG00000202041.
Homologues: Orthologues: chimpanzee Y_RNA (94% identical), macaque Y_RNA (93% identical). Paralogues in human: RNY1P5 (79% identical), Y_RNA (79% identical), Y_RNA (78% identical), Y_RNA (77% identical), Y_RNA (76% identical), Y_RNA (75% identical), RNY1P1 (74% identical), Y_RNA (74% identical), Y_RNA (73% identical), RNY1 (72% identical), Y_RNA (72% identical), Y_RNA (71% identical), and 90 more.